TCEAL8 (transcription elongation factor A like 8)
Description:
May be involved in transcriptional regulation.
Synonyms: MGC45400; WEX3
Tractability: PROTAC: ubiquitination databases record sites on it.
Gene: Protein-coding gene on chromosome X (103,252,863 to 103,255,204, reverse strand). Ensembl gene ENSG00000180964.
Subcellular location: Nucleus
Subcellular location (Human Protein Atlas): Nucleoplasm
Gene Ontology:
Molecular function: protein binding
Cellular component: nucleus
Homologues: Orthologues: chimpanzee TCEAL8 (100% identical), macaque TCEAL8 (97% identical), dog TCEAL8 (93% identical), rabbit TCEAL8 (87% identical), guinea pig TCEAL8 (85% identical), mouse Tceal8 (73% identical), rat Tceal8 (73% identical). Paralogues in human: TCEAL1 (42% identical), TCEAL9 (38% identical), TCEAL7 (38% identical), TCEAL3 (35% identical), TCEAL5 (35% identical), TCEAL6 (34% identical), TCEAL2 (32% identical), TCEAL4 (32% identical).
Diseases named in the same sentence as TCEAL8 in open-access papers:
TCEAL8 is named in the same sentence as 3 diseases in open-access papers, as found by Europe PMC text mining. Sharing a sentence is not in itself a finding about the gene and the disease. The quoted sentences say what the papers report.
gastric cancer (1 paper, 2013). A primary or metastatic malignant neoplasm involving the stomach. "A real-time quantitative PCR was performed on normal gastricepithelial cell line GES1 and gastric cancer cell lines including AGS, MKN45, MGC803, SGC7901 and HGC27 to determine the mRNA levels of TCEAL1, TCEAL3, TCEAL4, TCEAL5, TCEAL7 and TCEAL8." (PMID 23372750, 2013). "The TCEAL7 expression level was significantly lower in the gastric cancer cell lines comparing with the levels of TCEAL1, TCEAL3, TCEAL4, TCEAL5 and TCEAL8." (PMID 23372750, 2013).
Glucose intolerance (1 paper, 2022). Glucose intolerance (GI) can be defined as dysglycemia that comprises both prediabetes and diabetes. "Tceal8 was positively correlated with glucose intolerance of white blood cells and upregulated in HSHF-induced NAFLD and db/db mice." (PMID 35743193, 2022).
cancer (1 paper, 2025). A tumor composed of atypical neoplastic, often pleomorphic cells that invade other tissues. "Although the function of TCEAL8 in cancer was unknown, we found that TCEAL8 expression activated oxidative phosphorylation, protein export, ubiquitin mediated proteolysis, fatty acid metabolism, and antigen presentation through visium analysis of cancer tissues." (PMID 40448344, 2025).